BST2 (bone marrow stromal cell antigen 2)
Diseases named in the same sentence as BST2 in open-access papers (continued):
Sharing a sentence is not in itself a finding about the gene and the disease.
infection (continued). "In addition, both Huh7.5.1 and Huh7.5.1/BST2 cells exhibited similar kinetics and levels of viral RNA synthesis (both replication and transcription) following infection with LCMV as determined by Northern blot." (PMID 30028868, 2018). "Such an effect might be most relevant in situations where the viral antagonists of BST2 function are missing, for example after infection with nef-deleted SIV, where mechanisms acting before peak viremia determine disease progression." (PMID 26554913, 2015). "We next investigated whether the increased relative BST2 mRNA levels 24 weeks after infection also translated into increased BST2 protein expression." (PMID 26554913, 2015). "For example during initial infection locally produced IFN may increase BST2 expression on surrounding cells and thus limit early spread of the virus." (PMID 26554913, 2015). "Relative BST2 mRNA levels were significantly increased after infection (p < 0.0001)." (PMID 26554913, 2015). "This suggests that, once the infection is established, increased BST2 expression may favour viral dissemination by escaping host immune response." (PMID 26554913, 2015). "Here we have undertaken a comprehensive analysis of the role of endogenous BST-2 in restricting IAV infection by performing, to our knowledge, the first analysis of infection of BST-2-deficient primary murine cells with IAV and importantly, IAV infection of BST-2-deficient mice." (PMID 26566124, 2015). "In order to investigate the impact of SIV infection on BST2 transcription, relative BST2 mRNA levels in whole blood of 17 rhesus macaques were determined before and 24 weeks after infection with SIVmac251 using an intrarectal (i.r.)repeated low dose inoculation scheme." (PMID 26554913, 2015). "However, it is still possible that BST2 influences viral replication and the natural course of the infection under certain circumstances." (PMID 26554913, 2015). "Similarly, higher levels of BST2 were found in HIV-infected patients within the first 4 weeks of infection compared to chronic infection." (PMID 26554913, 2015). "Interestingly, this correlation was even better after normalizing relative BST2 mRNA expression levels to their individual pre-infection values (p < 0.01)." (PMID 26554913, 2015). "Furthermore, infection of activated primary human CD4+ T cells also showed a requirement of Vpu in BST2 down regulation and efficient production of infectious virus." (PMID 24195843, 2013). "A high MOI infection assay was performed to determine whether BST2 inhibits DENV entry in the cells." (PMID 23236425, 2012). "While DENV was freely transmitted in the infection system without restriction of 0.5% methocellulose, intracellular 4G2 protein markedly increased in all three cell lines at high MOI infection, whereas BST2 still moderately inhibited viral replication in Huh7-BST2 cells." (PMID 23236425, 2012). "Whether lower infection observed in BST-2 transfected cells is a result of cells being infected at low multiplicity or lower number of cells being infected is unclear." (PMID 22284121, 2012). "Furthermore, we treated each cell line with control siRNA (siGLO) or with siRNA to BST2 prior to infection with the HCMV strain Toledo." (PMID 22072961, 2011). "Unexpectedly however, we observed that BST2 had the opposite effect on infection by HCMV." (PMID 22072961, 2011). "Since BST2 is induced by IFN we were wondering whether HCMV would modulate IFN-independent and IFN-dependent BST2 gene induction during infection." (PMID 22072961, 2011). "The accumulation of virus clusters at the cell surface has been previously observed following infection of BST2-expressing cells with Vpu-defective HIV-1, suggesting that the effect of Rab7A knockdown on HIV release could be related to BST2 expression." (PMID 22072966, 2011).
infection (continued). "At the same time, if the goal of this activity is the continued recruitment of T cells to sites of infection, then the result of BST-2 downregulation might be expanded to include both enhanced viral egress and dissemination." (PMID 20485522, 2010). "Additionally, immunofluorescence experiments were performed with CD63 (a late endosome marker) antibodies, together with TGN46 and showcased that upon infection, BST2 is downregulated and mainly present in TGN46 positive compartments while less present in CD63 compartments." (PMID 39561185, 2024). "However, it is also possible that bst-2 SNPs rs919267 and rs9576 could impact the sensitivity of the cell to infection and therefore affect viral loads." (PMID 35081977, 2022). "By negating both intrinsic restriction factors (i.e., BST2 and SERINCs) and innate immune responses (i.e., pDC and NK(T) cell activity) during acute infection, Nef and Vpu are likely to promote both local replication at the site of initial infection and subsequent systemic spread." (PMID 26950141, 2016). "Given the requirement of Vpu-mediated BST2 antagonism for efficient innate immune evasion, it is tempting to speculate that control of pDC antiviral responses during early infection could also be important to ensure sufficient local viral expansion so that widespread dissemination could occur." (PMID 26172439, 2015). "Interestingly, induction of BST2 was also observed upon HCMV-infection." (PMID 22072961, 2011). "Among them, Bst2 shows a significant upregulation and reaches a peak one week after AAV-ie infection, as demonstrated by the transcriptome data." (PMID 41583531, 2026). "BST2 works to tether and retain viral particles at the cell surface of HIV-infected macrophages, therefore limiting propagation of infection." (PMID 41516395, 2026). "We clearly showed that RSV-mCherry ΔNS1 is significantly much more sensitive to BST2 restriction compared to RSV-mCherry at 48h and 72h post infection." (PMID 39561185, 2024). "The 17 DEGs upregulated after infection with huH1N1 were shared with the swH1N1 infection (DDX58 (RIG-I), RSAD2 (Viperin), MX2, MX1, OAS1, ANGPTL4, IRF7, ISG15, IFIT1, ISG12(A), DDX60, BST2, IFI44, XAF1, LGALS3BP, RTP4, and IFI6)." (PMID 39247193, 2024). "Depletion of Bst2+ cells or administration of TLR7 antagonists decreased lung immunopathology and morbidity, suggesting that pDCs play a deleterious role in this infection model." (PMID 38777879, 2024). "For this, ACE2-expressing A549 human lung epithelial cells were infected with the Hong Kong (HK) variant of SARS-CoV-2 or lentiviral-like particles (mock) at a multiplicity of infection (MOI) of 1 and BST2 expression was determined by RT-qPCR 6 hours later." (PMID 38190411, 2024). "We thus infected primary CD4+ T cells with CH058 TF; treated the cells with IFN-β (or PBS) 24 h later; and then examined BST-2, NTB-A, and CD48 expression 48 h post infection by flow cytometry." (PMID 37404017, 2023). "In particular, the expression of BST-2 and GATA-1 and their networks strongly suggest that women have stronger cell-dependent and humoral responses to infection, resulting in a more rapid pathogen elimination in females than in males." (PMID 34753980, 2021). "Infection with a UL26 deletion virus results in higher expression of both NF-κB target genes and ISGs, including ISG15 and bone marrow stromal cell antigen 2 (BST2)." (PMID 33096622, 2020). "Similar to A3G and BST-2, we found that HDAC10 levels decreased rapidly and were less than 50% at 48 h post infection." (PMID 31888084, 2019). "Infectious virus was then quantified at 48 h post infection by tissue culture infectious dose 50 (TCID50) titration, identifying an 80% reduction in virus yields when BST2 was overexpressed." (PMID 31366072, 2019). "Comparing BST-2 expression in PBMC from healthy donors or HIV-positive patients, Homann and colleagues showed that BST-2 increases as a result of HIV infection, in particular during the acute infection phase." (PMID 31426525, 2019).
infection (continued). "The restriction of MeV replication by BST2, or the two mutants, was assayed by TCID50 at 72 h post infection and demonstrated that removal of the GPI anchor from BST2 was sufficient to alleviate restriction of infectious MeV." (PMID 31366072, 2019). "The functional importance of early expression of this antiviral protein during LCMV infection was established in BST-2 KO mice, where we observed a failure to strictly confine LCMV Cl-13 to the splenic marginal zone at day three post-infection." (PMID 30028868, 2018). "In order to determine more precisely the kinetics upon infection, BST2 and MX1 transcription were assessed during the 1st weeks of infection in seven animals infected with different doses of SIVmac 251MPBMC as part of an in vivo titration study." (PMID 26554913, 2015). "Studies in humanized (hu) mice indicated that Vpu-mediated BST2 antagonism promoted HIV-1 replication and propagation in vivo, especially at early times post-infection when the predominant mode of viral transmission is likely to be by cell-free viruses." (PMID 26172439, 2015). "One week after infection, we observed a simultaneous increase of BST2 and MX1 transcripts in PBMC compared to pre-infection values, which reached a maximum at 10 days post infection (dpi)." (PMID 26554913, 2015). "Therefore, by limiting IFN-I and proinflammatory cytokines production by pDCs in the initial phase of infection, Vpu may contribute to the increased transmission fitness of T/F viruses by enabling efficient viral spread in an environment where expression of BST2 and other ISGs remain low." (PMID 26172439, 2015). "Together, these findings are consistent with the notion that Vpu-mediated BST-2 antagonism is critical for HIV-1 replication and propagation in vivo, especially at early times post-infection." (PMID 24195843, 2013). "Hence, BST-2 antagonism by Vpu during this critical phase would be required to ensure the efficient initial viral expansion by cell-free virus necessary for establishing infection, particularly in the face of a host environment where a strong antiviral IFN response is triggered early on." (PMID 24195843, 2013). "Collectively, our results suggest that Vpu-mediated BST-2 antagonism is critical for HIV-1 replication and propagation in vivo, especially at early times post-infection." (PMID 24195843, 2013). "Further analyses will be necessary to decipher the exact role of HRS in targeting BST-2 to the MVB pathway under physiological conditions and after infection by HIV-1, and the requirement for ubiquitination in these processes." (PMID 21304933, 2011). "BST2-expressing THFs or control THFs (THF-PCDH) were infected with an MOI of 3, and the supernatants were harvested at 72 hours post-infection (hpi)." (PMID 22072961, 2011). "BST2, ZBP1, CXCL11, and IFITM1 were involved in protein binding, and they are also broadly engaged in biological processes related to IFNs and responding to infections." (PMID 39874350, 2025). "Twenty-four hours post-infection, the culture supernatants were recovered to assess virion production in the presence and absence of BST2, which was measured by SARS-CoV-2 N-specific ELISA and infectivity assays (TCID50)." (PMID 38190411, 2024). "As BST2 was still downregulated following infection with RSVΔG, we concluded that G is not the viral protein responsible of BST2 antagonism." (PMID 39561185, 2024). "ORF7a can bind directly to the extracellular domain of BST-2 to block its glycosylation, and therefore BST2 could inhibit infection by icSARS-ORF7abΔCoV more efficiently than by icSARS-CoV." (PMID 35631059, 2022). "Moreover, BST-2 enhanced protective immune responses mediated by cells such as NK cells, CD4+ T cells and CD8+ T cells correlated with decreased infection levels." (PMID 35081977, 2022).
infection (continued). "The average methylation across the nine CpG sites was compared to BST-2 mRNA expression levels in samples with four different HIV serostatus or disease stages, i.e. pre-infection, 3, 12- and >36-months’ post-infection using n=27 matched ARV-naïve samples, based on sample availability." (PMID 34025670, 2021). "SERINC5, BST2, APOBEC and SAMHD1 are some of those factors highly ubiquitinated and therefore targeted to their degradation by viral proteins or under conditions of infection." (PMID 34835003, 2021). "We analyzed the interaction of BST-2 with several intracellular trafficking molecules 24 hours post infection with or without cocaine." (PMID 34530855, 2021). "This suggests that, for the virus, targeting BST-2 as part of its resistance to type I IFNs takes precedence over protecting HIV-1-infected cells from NK cell responses, at least early in infection, when type I IFN responses play an important role in systemic viral control." (PMID 31213558, 2019). "Alternatively, HIV-1-infected cells represent targets once infection is established, although in this case, CD4 downregulation and Tetherin/BST-2 antagonism could reduce HIV envelope ADCC-mediating epitope exposure." (PMID 29651286, 2018). "In contrast, BST-2 does not act according to its predicted role as a viral tetherin in several infection models." (PMID 26566124, 2015). "For macrophages, IAV titres did not increase between 2 and 24 hours following infection with either HKx31 or Brazil/78, and this was unaffected by the presence or absence of BST-2." (PMID 26566124, 2015). "Infection of BST-2-deficient mice with vesicular stomatitis virus, a target of BST-2 tethering in vitro, results in reduced, rather than increased, viral titers." (PMID 26566124, 2015). "Together, our data indicate that endogenous BST-2 does not play a major role in host restriction of IAV in the mouse model of infection." (PMID 26566124, 2015). "Our analyses rule out a major role for BST-2 as a host molecule that restricts IAV in the mouse model of infection." (PMID 26566124, 2015). "This study rules out a major role for endogenous BST-2 in modulating IAV in the mouse model of infection." (PMID 26566124, 2015). "In conclusion, based on our studies in the moue model of infection, it is likely that murine IAV infection and replication can be inhibited by the (combined) action of a number of host molecules, of which BST-2 may contribute only a minor role." (PMID 26566124, 2015). "Infection with the wild-type virus did not increase the expression of lncBST2/BISPR or BST2 (data not shown)." (PMID 25620967, 2014). "Bone marrow stromal cell antigen 2 (BST-2) is a cellular factor that restricts the egress of viruses such as human immunodeficiency virus (HIV-1) from the surface of infected cells, preventing infection of new cells." (PMID 22284121, 2012). "Similar to infection with untreated virus, increased amounts of pp71 were recovered from THF-HA146 infected with UV-inactivated virus as compared to THF-PCDH, whereas BST2 knockdown decreased recovery of pp65 from THF-HA146 infected with UV-inactivated HCMV." (PMID 22072961, 2011). "However, while we observed that HCMV counteracted the IFN-dependent induction of BST2, presumably as a result of interfering with JAK/STAT signaling, we observed that HCMV actually induced BST2 upon infection of fibroblasts." (PMID 22072961, 2011). "To determine whether BST2 facilitated HCMV entry into such primary cells, we knocked down BST2 by transfection of BST2-specific siRNA into monocytes and monitored pp65 or IE1 expression upon infection with HCMV-strain Toledo." (PMID 22072961, 2011). "Interestingly, we now extend that deletion of HIV-1 Nef, Vif, Vpr and Vpu, counteracting SERINC, APOBEC3, and BST-2, have no impact on cell-to-cell infection of macrophages by fusion with live infected T cells." (PMID 40294108, 2025).
infection (continued). "In agreement with IFN-I resistance of cell-to-cell infection of macrophages, IFNα-induction of APOBEC3G and 3A, Mx2, and likely other IFN-induced factors such as the Vpu-counteracted Bst-2/tetherin protein, does not affect macrophage infection by cell-cell fusion." (PMID 40294108, 2025). "Moreover, we showed that expression of viral proteins was not affected by BST2 siRNA treatment in a single round infection experiment performed at high MOI, validating that early steps of the viral cycle were not disturbed by BST2." (PMID 39561185, 2024). "BST2 protein is not detected in non-infected cells but is expressed at 3 days post-infection." (PMID 39561185, 2024). "This highlights the biological significance of BST2 in the absence of infection and provide a new mode by which BST2 may participate in immune response suppression." (PMID 36176574, 2022). "HIV replication was assessed by the amount of p24 released into tissue culture supernatant following infection of PBMCs from HIV negative individuals either having the highest (n=11) or lowest (n=11) BST-2 mRNA expression levels screened from a cohort of 65 HIV negative donors." (PMID 34025670, 2021). "Finally, we assessed whether these mutants also affect infectious MeV replication by performing a BST2-transfection, MeV-GFP infection experiment in permissive 293-hSLAM cells." (PMID 31366072, 2019). "To test the hypothesis that BST-2 is responsible for inhibition of MMTV release, we used an RNAi assay to determine whether silencing of endogenous BST-2 expression would lead to higher MMTV particle release and higher levels of infection." (PMID 22284121, 2012). "In vivo, BST2-mediated enhancement of HCMV entry may play a particularly important role in macrophages and dendritic cell that express BST2 upon differentiation in response to infection and inflammation." (PMID 22072961, 2011). "However, no study to date has directly addressed the impact of BST2 on SARS-CoV-2 during infection and whether the action-counteraction axis between the virus and this restriction factor has changed as new SARS-CoV-2 variants emerge." (PMID 38190411, 2024). "In agreement with Clare Jolly report, we did not see enhancement in HIV-1 ΔVpu cell coculture infection after pretreatment of Jurkat cells with IFNα (Zotova & Mazurov, unpublished data), which upregulated BST2 and could induce an antiviral cellular response as well." (PMID 31027334, 2019). "Interestingly, high MOI infection of DENV decreased the expression of BST2CV5 but not BST2." (PMID 23236425, 2012). "During footpad infection with ectromelia virus (ECTV), the administration of an anti-Bst2 antibody to deplete pDCs did not significantly increase mouse mortality." (PMID 38777879, 2024). "Ly6A/E expression was not impacted by anti-IFNγ treatment, but BST2 was significantly reduced, albeit modestly, in AT2 and CD24 + EC, the two major cell types that are targeted for infection by SARS-CoV-2." (PMID 38086794, 2023). "In the absence of BST-2, a persistent strain of LCMV was ineffectively contained in the spleen at early time points post-infection, resulting in impaired antiviral T cell responses and viral control systemically." (PMID 30028868, 2018). "Of interest, mouse models indicate that endogenous BST-2 does not play a major protective role following infection with either IAV or IBV, nor was endogenous BST-2 a major factor restricting IAV entry into or release from primary AEC or MΦ." (PMID 29215570, 2017). "Western blot revealed decreased expression of BST-2/tetherin, but not ISG15, in EV71-infected THP-1 and HT-29 cells at 12 and 24h post infection." (PMID 28910400, 2017). "In contrast, incubation (and infection) with IAV, increased surface BST-2 expression by macrophages, but not AEC." (PMID 26566124, 2015). "In this study, we demonstrate that BST2 expression did not effect viral replication and entry in Huh7 cells at high MOI infection." (PMID 23236425, 2012).